MND1 (meiotic nuclear divisions 1)
Description:
Required for proper homologous chromosome pairing and efficient cross-over and intragenic recombination during meiosis (By similarity). Stimulates both DMC1- and RAD51-mediated homologous strand assimilation, which is required for the resolution of meiotic double-strand breaks.
Synonyms: GAJ
Tractability: PROTAC: ubiquitination databases record sites on it.
Gene: Protein-coding gene on chromosome 4 (153,344,623 to 153,415,118, forward strand). Ensembl gene ENSG00000121211.
Subcellular location: Nucleus
Pathways (Reactome):
Reproduction: Meiotic recombination
Gene Ontology:
Molecular function: protein binding; double-stranded DNA binding
Biological process: homologous chromosome pairing at meiosis; reciprocal meiotic recombination
Cellular component: nucleus
Genetic constraint (gnomAD): Loss-of-function variants: 16 observed, 16.34 expected, observed/expected ratio (o/e) 0.98, 90% interval 0.66 to 1.49. The upper end of that interval is the gene's LOEUF score, 1.49, which puts it in group 6 of 6, group 1 being the genes least tolerant of losing a copy. Missense variants: 117 observed, 125.34 expected, observed/expected ratio (o/e) 0.93, 90% interval 0.8 to 1.09. Synonymous variants: 33 observed, 40.59 expected, observed/expected ratio (o/e) 0.81, 90% interval 0.62 to 1.09.
Homologues: Orthologues: chimpanzee MND1 (99% identical), guinea pig MND1 (92% identical), pig MND1 (92% identical), mouse Mnd1 (90% identical), rat Mnd1 (88% identical), tropical clawed frog mnd1 (77% identical), zebrafish mnd1 (63% identical).
Diseases named in the same sentence as MND1 in open-access papers:
MND1 is named in the same sentence as 27 diseases in open-access papers, as found by Europe PMC text mining. Sharing a sentence is not in itself a finding about the gene and the disease. The quoted sentences say what the papers report.
COVID-19 (4 papers, 2022 to 2024). A disease caused by infection with severe acute respiratory syndrome coronavirus 2. "Using published data, we use a set of optimized-performance COVID-19 genomic biomarkers (MND1, CDC6, ZNF282) to study the benefits and adverse effects of the BNT162b2 vaccine." (PMID 36366282, 2022). "As a result, it is safe to conclude that the five genes, ABCB6, KIAA1614, MND1, RIPK3, and SMG1, are truly COVID-19 specific, and the newly proposed classification method is a powerful tool." (PMID 35632517, 2022). "The expression level of MND1 has been cited as a critical gene for distinguishing patients with COVID-19 from patients without COVID-19." (PMID 36551164, 2022).
gastric cancer (3 papers, 2023 to 2025). A primary or metastatic malignant neoplasm involving the stomach. "MND1 is often overexpressed in various cancer types, including gastric cancer, and its high expression is linked to poor survival rates and advanced tumor stage." (PMID 41424711, 2025). "FOXA1 directly binds to the MND1 promoter to suppress its transcription, and this suppression-mediated activation of the PI3K/AKT signaling axis concomitantly inhibited gastric cancer progression and enhanced oxaliplatin chemosensitivity." (PMID 40623983, 2025).
lung adenocarcinoma (3 papers, 2021 to 2022). A carcinoma that arises from the lung and is characterized by the presence of malignant glandular epithelial cells. "In a recent study, genomic data from the GEO database that were further validated with clinicopathological data from the TCGA database revealed MND1 as a differentially expressed gene that significantly associated with overall survival of lung adenocarcinoma patients." (PMID 35251135, 2022). "Although less is known about MND1 in carcinogenesis, its aberrant expression has been reported in ovarian cancers and lung adenocarcinoma." (PMID 35251135, 2022). "The authors of the study therefore concluded that MND1 could be used as a prognostic biomarker and a molecular curative target for lung adenocarcinoma." (PMID 35251135, 2022).
lung carcinoma (3 papers, 2021 to 2022). "Several recent studies have demonstrated that MND1 messenger RNA (mRNA) levels are elevated in lung cancer and breast cancer, which means MND1 mRNA level is considered a prognostic factor for lung cancer and breast cancer." (PMID 36352167, 2022). "A study has previously demonstrated that MND1 can promote cell proliferation and migration in lung cancer and knockdown inhibits the proliferation and migration of lung cancer cells." (PMID 36352167, 2022). "Among them, MND1 was participated in several important pathways by connecting with other genes via 17 nodes in lung cancer, and more frequently expressed in LUAD patients with advancing stage (OR = 1.68 for stage III vs. stage I)." (PMID 33941804, 2021). "As previously reported, MND1 was highly expressed in both lung cancer and adenocarcinoma." (PMID 36352167, 2022). "In addition, MND1 has also been proven to promote the cell cycle in lung cancer by activating the KLF6/E2F1-positive feedback loop." (PMID 36352167, 2022). "Although it has been reported to be associated with lung cancer, breast cancer, and renal clear cell carcinoma, the relationship between MND1 and cancer has not been well explained." (PMID 36352167, 2022). "Meaningful clinical data were available for MND1, which has 17 nodes connected with other genes and participates in several pathways related to lung cancer, suggesting that MND1 might be essential in the progression of LUAD." (PMID 33941804, 2021).
renal clear cell carcinoma (3 papers, 2022). "Our results reveal the important function of MND1 in renal clear cell carcinoma and provide a potential link between MND1 and cell cycle, m6A, drug sensitivity, KIRC immune invasion and its underlying mechanism." (PMID 36098680, 2022). "Furthermore, MND1 was a prognostic biomarker for renal clear cell carcinoma." (PMID 36698420, 2022).
breast carcinoma (2 papers, 2019 to 2022). "One study reported an association between the high expression of MND1 and the immune microenvironment in breast cancer." (PMID 36352167, 2022).
colorectal cancer (2 papers, 2021 to 2024). A primary or metastatic malignant neoplasm that affects the colon or rectum.
hepatocellular carcinoma (2 papers, 2022 to 2023). A malignant tumor that arises from hepatocytes. "To determine the diagnostic value of MND1 in hepatocellular carcinoma, we constructed a receiver operating characteristic (ROC) plot using TCGA database." (PMID 36352167, 2022). "We validated the value of MND1 in evaluating the prognosis of hepatocellular carcinoma through a diagnostic and prognostic model." (PMID 36352167, 2022). "MND1 is one of the key hub genes among these genes and is associated with prognosis, so we further explored its role in hepatocellular carcinoma." (PMID 36352167, 2022). "In the present study, we analyzed the diagnostic value of MND1 in hepatocellular carcinoma using TCGA database and verified by in vitro experiments that MND1 may promote the progression of hepatocellular carcinoma by promoting proliferation and migration." (PMID 36352167, 2022). "These in vitro experiments demonstrate that knockdown of MND1 in hepatocellular carcinoma likely alleviates hepatocellular carcinoma progression by inhibiting proliferation and migration." (PMID 36352167, 2022). "In this study, we analyzed the role of MND1 in prognostic diagnosis through TCGA database and demonstrated that MND1 has prognostic value in hepatocellular carcinoma." (PMID 36352167, 2022). "At the same time, cellular experiments were used to demonstrate the effect of MND1 on hepatocellular carcinoma proliferation and migration." (PMID 36352167, 2022). "We analyzed the correlation between the mRNA expression level of MND1 and the clinical characteristics of hepatocellular carcinoma patients through an online database." (PMID 36352167, 2022). "At the same time, we also verified the expression of MND1 in hepatocellular carcinoma with the online database GEPI2A, which also showed high expression." (PMID 36352167, 2022). "We also performed overexpression experiments to prove that MND1 promotes the proliferation and migration of hepatocellular carcinoma." (PMID 36352167, 2022). "We also conducted in vitro experiments to explore the effect of MND1 knockdown on hepatoma cell lines." (PMID 36352167, 2022). "We also found that MND1 is highly expressed in hepatocellular carcinoma and verified the high expression of MND1 in hepatocellular carcinoma cell lines." (PMID 36352167, 2022). "To explore genes coexpressed with MND1 in hepatocellular carcinoma, we performed coexpression analysis using LinkedOmics." (PMID 36352167, 2022). "At the same time, the mechanism by which MND1 leads to the progression of hepatocellular carcinoma remains to be further studied, and we will conduct more in-depth research on this topic in future." (PMID 36352167, 2022). "In our research, by knocking down MND1 in liver cancer cell lines, we confirmed that knockdown could affect the phenotypes of hepatocellular carcinoma, such as proliferation and migration." (PMID 36352167, 2022). "Therefore, in general, MND1 is expected to be a gene that can effectively diagnose and treat hepatocellular carcinoma." (PMID 36352167, 2022). "Furthermore, we used the UALCAN database to explore the relationship between MND1 and the pathological features of hepatocellular carcinoma patients." (PMID 36352167, 2022). "Furthermore, we used Western blotting and qPCR to explore MND1 expression in different hepatoma cell lines." (PMID 36352167, 2022). "To further explore the role of MND1 in hepatocellular carcinoma, we performed in vitro experiments." (PMID 36352167, 2022). "However, there are few studies of MND1 in other cancers, especially in hepatocellular carcinoma, and the biological role of MND1 remains unclear." (PMID 36352167, 2022).
Azoospermia (1 paper, 2013). Absence of any measurable level of sperm,whereby spermatozoa cannot be observed even after centrifugation of the semen pellet. "In this work, we used the specimens from testicular biopsies of men with non-obstructive azoospermia who underwent TESE to investigate the expression of spermatogenesis-related genes MND1, SPATA22, GAPDHS and ACR." (PMID 23675907, 2013).
cyst (1 paper, 2024). A sac-like closed membranous structure that may be empty or contain fluid or amorphous material. "RAD21, SMC3, and MEI2 are linked to bloom-promoting sex, HOP2 and MSH4 to cyst germination, while SPO11, MND1, and DMC1 are common to both cyst-forming and non-encysting sex." (PMID 39367346, 2024).
glioma (1 paper, 2022). A benign or malignant brain and spinal cord tumor that arises from glial cells (astrocytes, oligodendrocytes, ependymal cells). "After calculating the hazard ratio and confidence interval, we observed that 8 hub genes in hub network 1 were related to the poor prognosis of gliomas, including PBK, KIF2C, CENPE, KIF14, MND1, FAM83D, NEIL3, and CDKN3." (PMID 35387222, 2022).
leukemia (1 paper, 2025). A malignant (clonal) hematologic disorder, involving hematopoietic stem cells and characterized by the presence of primitive or atypical myeloid or lymphoid cells in the bone marrow and the blood. "In leukemia, MND1 interacted with other proteins such as TKT to regulate tumor progression, and it modulated chemotherapy sensitivity by PI3K/AKT signaling pathway." (PMID 41424711, 2025).
liver cancer (1 paper, 2022). An epithelial or non-epithelial malignant neoplasm that arises from the liver. "Since knockdown of MND1 promotes the progression of liver cancer cell lines, we wondered whether overexpression of MND1 in liver cancer cell lines would promote its progression." (PMID 36352167, 2022).
metastatic prostate carcinoma (1 paper, 2022). A carcinoma that arises from the prostate gland and has spread to other anatomic sites. "It demonstrates a tightly associated sub-network of the meiotic cell cycle with strictly meiosis-specific (i.e., HORMAD1, MND1, SMC1B) genes and includes CT genes such as TTK and PBK (known also for metastatic prostate carcinoma)." (PMID 36499258, 2022).
schizophrenia (1 paper, 2025). A major psychotic disorder characterized by abnormalities in the perception or expression of reality. "However, several VMPs exhibited opposite patterns of variance between blood and brain regions, including some within the GRIK3, GFI1, ADRB3 and MND1 genes, amongst others, indicating that some schizophrenia associated VMPs may exhibit divergent variance patterns between the periphery and brain." (PMID 39271751, 2025).
cancer (11 papers, 2011 to 2025). A tumor composed of atypical neoplastic, often pleomorphic cells that invade other tissues. "Meiotic Nuclear Divisions 1 (MND1) plays a role in homologous recombination (HR) during meiosis and has been implicated in DNA repair in cancer." (PMID 41424711, 2025). "MND1 and 36 genes significantly correlated with MND1 in KIRC collected by PPI, were used for cancer pathway and drug susceptibility analysis." (PMID 36098680, 2022). "By performing a differential mRNA expression analysis of normal versus malignant ovarian tumors, P.N. Yeganeh and colleagues identified MND1 as one of the most significantly dysregulated genes in the malignant tissues." (PMID 35251135, 2022). "Using a genome-wide insertional mutagenesis screen in somatic cancer cells, we identified MND1 as a factor which increases cellular fitness following exposure to irradiation (IR)." (PMID 35251135, 2022). "Based on the GEPIA tool, MND1 was found to be overexpressed in various types of cancer." (PMID 37817120, 2023). "It illustrated that MND1 was upexpressed in many types of cancer tissues than normal tissues." (PMID 36098680, 2022). "MND1 is a gene that plays a vital role in meiosis, but its relationship with cancer is unclear." (PMID 36352167, 2022). "In our study, we analyzed the expression of MND1 in various cancers." (PMID 36352167, 2022). "The results showed that MND1 was highly expressed in many cancers." (PMID 36352167, 2022). "These recommend that MND1 may function as a target for early clinical diagnosis and treatment, and at the same time provide a reference for further exploration of new cancer immunotherapy." (PMID 36098680, 2022). "MND1 is a meiosis specific protein that participates in the progress of diverse cancers." (PMID 36098680, 2022). "Examples include the HORMAD1/2, MND1, MEIOB and SYCP3 genes, which directly influence the HR activity of cancer cells." (PMID 35251135, 2022). "Hence, MND1 may be an interesting drug target to sensitize somatic cancers to DSB-inducing therapy." (PMID 35251135, 2022). "To explore the expression of MND1 in tumor and nontumor tissues, we used the Oncomine database to analyze the expression of MND1 in different cancers." (PMID 36352167, 2022). "As shown in our result, these genes, especially MND1, could activate Apoptosis, Cell Cycle, DNA Damage Response, EMT, Hormone AR and inhibit Hormone ER, PI3K/AKT, RAS/MAPK, RTK pathways to play a regulatory role in the cancer process." (PMID 36098680, 2022). "However, no other studies have demonstrated the role of MND1 in other cancers." (PMID 36352167, 2022).
tumor (9 papers, 2015 to 2025). "Overall, high levels of MND1 may be associated with tumor stage and worse survival." (PMID 36352167, 2022). "LEfSe analysis showed that Acidobacteriota, Nitrosomonadaceae, Rhizobiales, Actinobacteria, Burkholderiales, Gammaproteobacteria, MND1, and Proteobacteria were more abundant in the tumour than in the adjacent non-tumour group." (PMID 39553581, 2024). "Here owing to the expression level of MND1, we demonstrated that there are 6 types of tumor-infiltrating immune cells in KIRC tissues." (PMID 36098680, 2022). "After adjusting for tumor purity, the MND1 expression level was obviously relevant to 16 out of 33 immune cell markers in KIRC." (PMID 36098680, 2022). "These genes are suggested to be significantly associated with biological activities, such as the cell cycle and cell division, which means that MND1 is one of the crucial genes in tumor progression." (PMID 36352167, 2022). "Then, to analyze the amount of MND1 expression in normal tissues and tumor tissues, the Wilcoxon rank sum test was adopted to draw differential expression maps and paired differential expression map." (PMID 36098680, 2022). "In conclusion, these results proclaimed that MND1 was related to tumor cell infiltration in KIRC." (PMID 36098680, 2022). "Besides, we also delved into the connection between MND1 expression and cell cycle, tumor infiltrating immune cells, m6A, drug sensitivity in KIRC patients." (PMID 36098680, 2022). "We found that MND1 had a higher expression in tumor tissue where distant metastasis occurred." (PMID 36098680, 2022). "Also, the analysis result revealed that the expression of MND1 was positive correlated with T (Tumor size)." (PMID 36098680, 2022). "Additionally, the expression of MND1 was closely related to tumor grade of KIRC and was positive correlated with it." (PMID 36098680, 2022). "Thus, our work demonstrated MND1 regarding Tumor Purity as well as immune infiltration level in KIRC." (PMID 36098680, 2022). "Therefore, we had reasons to speculate that the high expression of MND1 can promote the proliferation, invasion and metastasis of tumor tissues through increasing the expression of some chemokines." (PMID 36098680, 2022). "Finally, we also found that MND1 expression increased in tumor tissue with lymph node metastasis." (PMID 36098680, 2022). "Previous studies suggest that MND1 may be a powerful target for tumor therapy." (PMID 36352167, 2022). "In particular, our data highlighted MTFR2, MND1, FAM72D, and POC1A as genes whose expression correlates with worse OS prognosis, suggesting their possible involvement in tumor progression and invasion." (PMID 31067633, 2019). "mRNA patterns of AKT3 suggest essential connections with tumor growth and metastasis, as well as a strong biomarker potential when used with 3 other genes (PTTG1, MND1, CENPF)." (PMID 29321820, 2017). "Intriguingly, FOXA1 and BMI1 exhibit opposing roles in modulating the PI3K/Akt pathway: BMI1 activates PI3K/Akt signaling to drive tumor growth and chemoresistance, whereas FOXA1 suppresses MND1 to inhibit progression and enhance oxaliplatin sensitivity via the same pathway." (PMID 40623983, 2025). "Several studies have found that MND1 may be a new target for tumor therapy, but they have not studied the role of MND1 in tumors in depth." (PMID 36098680, 2022).
MND1 also shares sentences with these, for which no sentence is quoted: lymph node metastasis (2 papers); ovarian carcinoma (2); adenocarcinoma (1); bladder cancer (1); melanoma (1); non-small cell lung carcinoma (1); ovarian dysfunction (1); ovarian dysgenesis (1); pancreatic cancer (1); small cell lung carcinoma (1).